ANXA2 (annexin A2)
Diseases named in the same sentence as ANXA2 in open-access papers (continued):
Sharing a sentence is not in itself a finding about the gene and the disease.
ovarian carcinoma (continued). "Response to ATRA treatment in the ovarian cancer cell lines did not correlate with expression of ANXA2, S100A10 or retinoic acid receptor alpha (RARA) as all cell lines exhibited similar gene expression levels." (PMID 30621740, 2019). "A greater understanding of the functional role of S100A10 in ovarian cancer cells could lead to the development of effective strategies to target S100A10 and annexin A2, inhibit progression, and overcome chemotherapy resistance in ovarian cancer patients." (PMID 30572596, 2018). "The Endo28-3WJ-Sph1/Dox particles were delivered to annexin-2-positive IGROV-1 (71%) and SKOV-3 (52%) ovarian cancer cell lines, with very little binding (17%) to annexin-A2-negative human embryonic kidney 293 (HEK293) cells." (PMID 28703779, 2017). "In the present study, we showed that annexin II (ANXA2), a specific binding partner of HE4, is expressed in ovarian cancer cells, and the interaction between HE4 and ANXA2 promotes the invasion and metastasis of ovarian cancer cells via the MAPK and FOCAL signaling pathways." (PMID 25362534, 2014). "The present study is the first to demonstrate the structural relationship between HE4 and ANXA2, which led to the hypothesis that HE4 and ANXA2 binding promotes ovarian cancer cell invasion and metastasis." (PMID 25362534, 2014). "To test this hypothesis, we generated ovarian cancer cell lines with high and low HE4 expression and showed that the up- or downregulation of HE4 was accompanied by parallel changes in ANXA2 expression in the treated cell lines." (PMID 25362534, 2014). "Confocal laser scanning microscopy showed the co-localization of the HE4 and ANXA2 in the two ovarian cancer cell lines ES-2 and CaoV-3 (some results are not shown)." (PMID 25362534, 2014). "However, the function and mechanism of exosomal ANXA2 on peritoneal implantation of ovarian cancer have not been fully elucidated." (PMID 34725902, 2021). "ANXA2 and human epididymis protein 4 (HE4) are interacting proteins, and the binding between them can activate various signaling pathways, such as the MAPK and FOCAL pathways, thereby promoting the invasion, metastasis, and epithelial-mesenchymal transition (EMT) of ovarian cancer cells." (PMID 31474227, 2019). "In addition, we analyzed the differential mRNA expression levels of Annexins between ovarian cancer and normal ovarian tissues using the GEPIA database, which indicated that ANXA2, ANXA3, and ANXA11 mRNA expression levels were significantly upregulated in ovarian cancer." (PMID 31474227, 2019). "Elucidation of the biological functions of HE4 will reveal the mechanisms underlying the role of HE4 in the development, invasion and metastasis of ovarian cancer and may lead to the design of therapeutic strategies targeting HE4 and ANXA2 for the treatment of ovarian cancer." (PMID 25362534, 2014). "Moreover, a large scale proteomic study identified annexin A2 to be upregulated in ovarian cancers when compared with normal ovarian tissue and benign lesions." (PMID 23945256, 2013). "Meanwhile, univariate and multivariate Cox regression analyses were performed on ANXA2P2 for ovarian cancer, manifesting that the pseudogene ANXA2P2 can be used as an independent prognostic factor without relying on ANXA2." (PMID 35211410, 2022). "While the effects of ATRA on ovarian cancer proliferation and apoptosis have been previously investigated, to date no data has been reported on the effects of ATRA on both annexin A2 and S100A10 expression in serous ovarian cancer cells." (PMID 30621740, 2019). "While the effects of ATRA on ovarian cancer cell proliferation and apoptosis have been previously investigated, to date no data has been reported on the effects of ATRA on both annexin A2 and S100A10 expression in ovarian cancer cells." (PMID 30572596, 2018).
ovarian carcinoma (continued). "Although is not clear why ovarian cancer cell lines are resistant to ATRA treatment, our study suggests that resistance to ATRA treatment is not dependent on RARA, ANXA2 or S100A10 expression as all of the serous ovarian cancer cell lines expressed similar mRNA levels of these genes." (PMID 30621740, 2019).
prostate carcinoma (50 papers, 2007 to 2026). A carcinoma that arises from epithelial cells of the prostate gland. "This study confirms the potential for use of archival FFPE specimens in the search for prognostic biomarkers for prostate cancer and suggests that annexin A2 abundance in diagnostic biopsies is predictive for metastatic potential." (PMID 26388710, 2015). "In fact, immunohistochemistry of prostate cancer patient samples showed a loss in expression of annexin A2 and its binding partner S100A10 in all patients." (PMID 23519104, 2013). "In addition, annexin A2 and Hsp90 have been reported to be associated with the development of prostate cancer by promoting the growth process." (PMID 31889151, 2019). "More meaningfully, some clinical studies have shown the relationship between the expression levels of ANXA2 and the invasion and metastasis of prostate cancer." (PMID 36936694, 2023). "In prostate cancer, ANXA2 expression is reduced or lost in cell lines, and its overexpression inhibited cell migration." (PMID 36247003, 2022). "Further, our in silico analysis revealed that the survival ability of the prostate cancer patients is poor with the increased expression of ANXA2 along with the high (> 6.0) gleason score." (PMID 36224238, 2022). "Additional evidence for roles of AnxA2 in the tumour microenvironment came from the inoculation of prostate cancer cells with bone marrow stromal cells from the AnxA2 KO-mice." (PMID 33810523, 2021). "For instance, ANXA2 was found to be abundantly expressed in primary normal human prostate epithelial cells, but significantly reduced or lost in prostate cancer cell lines." (PMID 32823855, 2020). "ANXA2 was distributed in both the cytosol and underneath the plasma membrane in normal prostate epithelial cells, while prostate cancer cells showed reduced or lost expression in prostate cancer development and progression." (PMID 32823855, 2020). "An annexin A2 peptide containing the S100A10 binding site prevents the binding of prostate cancer cells and multiple myeloma cells to osteoblasts." (PMID 30572596, 2018). "S100A10 together with annexin A2 has been shown to regulate the adhesion of leukemia cells and prostate cancer cells to osteoblasts." (PMID 30572596, 2018). "Secretion of IL-6 is dramatically decreased in prostate cancer cells upon ANXA2 knockdown, while overexpression of naive ANXA2 increases IL-6 secretion." (PMID 25611381, 2015). "In a clinical study, the ANXA2 expression is significantly lower in prostate cancer compared to benign prostatic hyperplasia (P < 0.01)." (PMID 24591759, 2014). "Recently, ANXA2/ANXA2 receptor axis has been shown to promote the adhesion of prostate cancer to osteoblasts and endothelial cells." (PMID 24591759, 2014). "In prostate cancer cells, AnxA2 physically interacts with STAT6 to stabilize cytosolic levels of phosphorylated STAT6 and promote its nuclear localization." (PMID 25222280, 2014). "Knockdown of ANXA2 inhibits interleukin (IL)-6 secretion in a prostate cancer model under starvation stimulation conditions." (PMID 24591759, 2014). "ANXA2 is required for the growth of prostate cancer and acts through the MAPK pathway or by upregulating IL-6 secretion." (PMID 24591759, 2014). "ANXA2 heavy (p36) and light (p11) chains in 31 of 31 prostate cancer specimens are undetectable by immunohistochemistry, suggesting a loss of ANX2A expression in cancer cells, whereas basal cells are positively stained." (PMID 24591759, 2014). "It has been reported that AnxA2 associates with signal transducer and activator of transcription 6 (STAT6) and stimulates STAT6 transcriptional activity in prostate cancer cells." (PMID 25222280, 2014). "Ser-25 and Ser-11 phosphorylation of annexin A2 also prevents the nuclear shuttling of the protein in prostate cancer cells." (PMID 23519104, 2013). "Annexin A2 can also facilitate the growth of prostate cancer cells in vitro through activation of the MAPK pathway." (PMID 23519104, 2013).
prostate carcinoma (continued). "In contrast, the expression of ANXA2 is lost or reduced in prostate cancer, and the role of ANXA2 in prostate cancer appears contradictory." (PMID 23950866, 2013). "Annexin A2 mRNA expression is often lost in prostate cancer specimens when compared to normal prostate tissues." (PMID 23519104, 2013). "PLGA (poly lactide-co-glycolide) nanoparticles loaded with annexin A2 shRNA vector can mediate long-term silencing of annexin A2 and are able to reduce tumor growth in xenograft models of prostate cancer." (PMID 23519104, 2013). "From studies of prostate cancer, ANXA2 upregulation is expected since in vitro experiments indicate that overexpression promotes a more invasive, proliferative cell phenotype." (PMID 20824133, 2010). "Dysregulation of ANXA2 has been reported in human bone cancer metastases and is correlated with the clinical prognosis of prostate cancer." (PMID 17411443, 2007). "ANXA2 can therefore be used as a prognostic biomarker for aggressive prostate cancer." (PMID 36936694, 2023). "The protein Annexin A2 has been explored as a prognostic marker because of the expression of this protein in various cancer cells including oral squamous cell carcinoma and prostate cancer." (PMID 37189694, 2023). "In addition, studies have demonstrated the function of ANXA2 in regulating the adhesion of hematopoietic stem cells to osteoblasts and bone marrow endothelial cells and the adhesion of prostate cancer cells to endothelial cells." (PMID 34484309, 2021). "In cases involving prostate cancer cells, the ANXA2/ANXA2R axis and the GAS6-AXL interaction, which both induce dormancy of cancer cells in the bone microenvironment, may represent rational targets for the therapy of skeletal metastasis." (PMID 34831167, 2021). "ANXA2 re-expression inhibited prostate cancer cell migration." (PMID 32823855, 2020). "However, there are also some researchers who hold the opposite view that S100A10 and Annexin A2 are positively correlated with the malignancy of prostate cancer." (PMID 31949486, 2020). "However, in some high-grade tumors, ANXA2 facilitates the adhesion-dependent or -independent growth of prostate cancer through the MAPK pathway or interleukin-6 (IL-6) secretion." (PMID 24591759, 2014). "However, annexin A2 down-regulation have been reported in some cancers (prostate cancer and head and neck cancers), yet some of these results remain conflicting mainly due to difference in methodologies." (PMID 23519104, 2013). "Moreover, serum containing overexpressed ANXA2 showed higher levels of IL-6; the siRNA-mediated inhibition of ANXA2 expression in prostate cancer cells reduced IL-6 secretion, while the restoration of ANXA2 expression by transfection of the ANXA2 gene normalized IL-6 secretion." (PMID 39057791, 2024). "Currently, lower ANXA2 expression in prostate cancer patients, compared to that in benign prostatic hyperplasia, correlates with an advanced clinical stage, more frequent recurrence, and regional lymph node and distant metastasis and may serve as a useful biomarker." (PMID 24591759, 2014). "Another report demonstrated that thereduction in cell surface ANXA2 expression in response to changes in interferongamma levels leads to reduced prostate cancer cell invasion, suggesting that the cellsurface translocation of ANXA2 may be an important cellular process for multipletypes of cancers." (PMID 21572519, 2011). "While the expression of other prostate cancer EMT markers HAS-3, AHNAK2, TGFBR2, ANXA2, and ANXA3 was higher in DU145 compared with DUTXR (Fig. 1CII–IV)." (PMID 37476073, 2023). "Our scRNA-seq analysis detected greater expression of ANXA3, ANXA2, ANXA2P2, and AHNAK2 in aggressive prostate cancer." (PMID 37476073, 2023). "Annexin A2 (ANXA2)/annexin A2 receptor (ANXA2R) interactions between osteoblasts or endothelial cells and circulating prostate cancer cells have also been reported to support homing and adhesion to bone." (PMID 34831167, 2021).
prostate carcinoma (continued). "ANXA2 expression is decreased in esophageal squamous cell carcinoma (ESCC), osteosarcoma, and prostate cancer." (PMID 24591759, 2014). "ANXA2 expression is also reduced or lost in prostate cancer cell lines, such as LNCAP, PC3, and DU145, and so forth, compared with primary normal human prostate; however, overexpression of ANXA2 in DU145 or LNCaP inhibits cell migration." (PMID 24591759, 2014). "EVs from individuals with prostate cancer typically include cancer-related proteins such as CD9, CD81, and TSG101, as well as Annexin A2, Fatty Acid Synthase (FASN), and a prostate cancer-specific biomarker termed FOLH1 (Prostate Specific Membrane Antigen or PSMA)." (PMID 36059497, 2022). "In prostate cancer, ANXA2 module inversely correlated with ERG in its network and can be used for biological stratification and therapeutic targeting of ERG based stratification of prostate cancers." (PMID 33575208, 2020). "Similarly, a previous study showed that Anxa2 binds to STAT6 and promotes its activity in prostate cancer cells." (PMID 26307676, 2015). "The ACE4 aptamer do not bind PC3 cells established from human prostate carcinoma suggesting this cell line do not express Annexin A2." (PMID 24489826, 2014). "More recently, a retrospective study of patient samples with non-metastatic prostate cancer revealed that all annexin A2-positive tumors (n = 40) relapsed compared to only half in annexin A2-negative tumors." (PMID 23519104, 2013). "Expectedly, retroviral re-expression of annexin A2 in prostate cancer cells (DU-145 and LNCaP) with low/no endogenous annexin A2 significantly inhibited migration of both cell lines." (PMID 23519104, 2013). "In fact, aberrant expression of ANXA2 is somehow related to the carcinogenesis of human cancers, because it has been shown to be clearly absent in some prostate cancers and highly overexpressed in other human cancers." (PMID 21918681, 2011). "In the balanced differentiated group of young and old prostate cancer patients, MYC and HDAC1 genes were emerged as a central node and uniquely upregulated in young men whereas VEGFA is the key node in old men and found to be down regulated along with HLA and ANXA2 genes in old patients." (PMID 33575208, 2020). "However, the overexpression of ANXA2-green fluorescent protein in DU145 prostate cancer cells does not affect cell-cycle progression, as assessed by BrdU incorporation assays." (PMID 24591759, 2014). "In addition, VEGF induces Tyr phosphorylation and nuclear translocation of Activator of Transcription 6 (STAT6), which interacts with AnxA2 in prostate cancer cells, suggesting that one of the angiogenic effects of VEGF is to regulate the expression of AnxA2 directly or indirectly." (PMID 23555942, 2013). "Microarray analysis revealed that annexin A2 (along with annexin A1, A4, A7 and A11) was significantly down-regulated in metastatic androgen-independent prostate cancer patients when compared to hormone-naive prostate cancers and non-cancerous prostate tissues." (PMID 23519104, 2013). "To assess more definitively the inhibitory effect of ANXA2 on the frameshifting of IBV pseudoknot RNA, we used a prostate cancer cell line, LNCaP, which does not express endogenous ANXA2 protein in the cells." (PMID 21918681, 2011).
lung carcinoma (49 papers, 2009 to 2025). "In 2012, David M. Waisman and his colleagues indicated that the ANXA2 protein was imported into nuclei to protect against DNA damage caused by irradiation in human breast and lung cancer cells." (PMID 29598816, 2018). "We identified aptamer-associated protein biomarkers for lung cancer such as vimentin, annexin A2, annexin A5, histone 2B, neutrophil defensin, and clusterin." (PMID 26061649, 2015). "As a calcium-dependent phospholipid plasma membrane-binding protein, ANXA2 is overexpressed in various tumor tissues, including lung cancer and cholangiocarcinoma tissues, and is closely associated with tumor cell proliferation, apoptosis, invasion, and metastasis." (PMID 39972459, 2025). "In conclusion, our results indicated that HAR1A deficiency disables the ubiquitination and proteasomal degradation of ANXA2 to activate the NF-κB pathway, leading to lung cancer progress." (PMID 38688909, 2024). "These included annexin A1(ANXA1) and annexin A2 (ANXA2), both known to be associated with lung cancer." (PMID 38539567, 2024). "ANXA2 is also associated with several classical cancer-related pathways such as PI3K/Akt signaling, Akt/mTOR signaling, and NF-κB signaling pathways in lung cancer, gastric cancer, and GBM respectively." (PMID 38658569, 2024). "Collectively, TIM-4 promotes oxidative phosphorylation of lung cancer cells to accelerate tumor progress via ANXA2/PI3K/AKT/OPA1 axis, which sheds significant new lights on the potential role of TIM-4 in regulating tumor cell metabolism." (PMID 36806050, 2023). "Mutual Co-IP confirmed that TIM-4 physically interacted with ANXA2 in the two lung cancer cell lines." (PMID 36806050, 2023). "Mechanistically, ANXA2/PI3K/AKT signaling pathway was responsible for TIM-4 mediated regulation of mitochondrial function in lung cancer cells." (PMID 36806050, 2023). "ANXA2 ELISA was performed on NSCLC resection specimens (n = 9), demonstrating that human lung cancers possess a high concentration of ANXA2 protein and lending physiological relevance to the stimulation assays." (PMID 36377658, 2022). "S100-A8, thymidine phosphorylase, annexin A2, transglutaminase 2, and annexin A1 were lung cancer individuals’ most renowned over-expressed proteins." (PMID 36552956, 2022). "A phospholipid-binding protein called annexin A2 (ANXA2) is recently reported to be released to the extracellular matrix via Rab11 in an autophagy-dependent regulation under IFN-γ stimulation in lung cancer cells." (PMID 35927755, 2022). "Further studies found that SETDB1 functionally cooperated with the TGFb-regulated complex SMAD2/3 to inhibit the expression of Annexin A2 (ANXA2), which plays a crucial role in lung cancer metastasis." (PMID 34299035, 2021). "Chlorogenic acid has been reported to inhibit the proliferation of human lung cancer (A549) cell lines by targeting annexin A2 in vitro and in vivo." (PMID 34960117, 2021). "This study focused on the role of circRNA ANXA2 (circANXA2) in lung cancer and the molecular mechanism of cancer promotion." (PMID 34992655, 2021). "The association of SETDB1 with Smad3 has been also shown to suppress metastasis in lung cancer by repressing IL-2 and the Ca2+-dependent RNA-binding protein annexin A2 (ANXA2) that interacts with the mRNA of the nuclear oncogene, c-myc." (PMID 33803458, 2021). "A study reported that ectopic expression of miR-1-3p in lung cancer cells suppresses proliferation, impairs cell cycle progression, and inhibits migration and invasion ability by silencing ANXA2 expression." (PMID 33266425, 2020). "Increased expression of AnxA2 appears to correlate with tumor invasiveness in renal cell carcinoma, hepatocellular carcinoma, colorectal cancer and lung cancer." (PMID 32575495, 2020). "The displacement of S100A10 from annexin A2 attenuates plasminogen activation, impairing colony formation and growth of A549 lung cancer cells." (PMID 30572596, 2018).